MIR1266 (microRNA 1266)
Synonyms: hsa-mir-1266; MIRN1266; mir-1266
Gene: MicroRNA gene on chromosome 15 (52,277,117 to 52,277,200, reverse strand). Ensembl gene ENSG00000221052.
Homologues: Orthologues: chimpanzee ptr-mir-1266 (100% identical).